SUCNR1 (succinate receptor 1)
Diseases named in the same sentence as SUCNR1 in open-access papers (continued):
Sharing a sentence is not in itself a finding about the gene and the disease.
cancer (continued). "SUCNR-1 expression is increased in human SDH-mutated tumors and several common cancers, which is associated with a high risk of metastasis and a high risk of recurrence following surgery." (PMID 36344992, 2022). "Cancer-derived extracellular succinate enhances cancer cell and macrophage migration through SUCNR-1 → PI-3 K → HIF-1α pathway." (PMID 36344992, 2022). "The reported findings suggest that succinate acts in an autocrine and paracrine manners to drive cancer metastasis via the SUCNR-1 → PI-3K → Akt → HIF-1α signaling pathway." (PMID 36344992, 2022). "Extracellular succinate augments cancer growth and metastasis through SUCNR-1 mediated signaling pathways and transcription programs." (PMID 36344992, 2022). "Succinate increases SUCNR-1 expression in cancer cells which is considered as a target for developing new anti-metastasis drugs." (PMID 36344992, 2022). "Unfortunately, there is still a scarce number of functional studies analyzing the specific role of SUCNR1 in different types of cancer." (PMID 33113952, 2020). "Previous work revealed a mutual dependence of SUCNR1 expression and cancer cell metabolism." (PMID 39838520, 2025). "Similarly, succinate secreted by cancer cells is reported to activate SUCNR1 signaling, converting murine peritoneal macrophages into the M2-polarized form." (PMID 40559534, 2025). "Additionally, besides this direct impact of the SDH subunits on EMT phenotypes, another study claimed their indirect role mediated via subsequent succinate accumulation that favors EMT and cancer cell migration via Succinate Receptor 1 (SUCNR1)." (PMID 37899663, 2024). "SUCNR-1 mediates physiological roles, such as immune responses, glucose homeostasis, hematopoiesis, and platelet aggregation, and pathological conditions, such as tissue injury, inflammation, fibrosis, and cancer metastasis." (PMID 37446354, 2023). "The purpose of this review is to address the underlying mechanism of succinate accumulation in and secretion from cancer cells, actions of succinate on cancer cell migration, invasion and metastasis and the potential value of SUCNR-1 as a target for developing new anti- metastatic therapy." (PMID 36344992, 2022). "Given that mitochondrial fragmentation in cancer cells is associated with increased migration and metastasis, it is possible that succinate/SUCNR-1 → mitochondrial fragmentation pathway may provide additional force to drive cancer metastasis." (PMID 36344992, 2022). "It is important to determine whether serum succinate is a theranostic biomarker for selecting cancer patients for anti-SUCNR-1 drug therapy." (PMID 36344992, 2022). "Emerging evidence points to succinate as an important oncometabolite in cancer development; however, the contribution of the succinate-SUCNR1 axis to cancer progression remains unclear." (PMID 33916314, 2021). "Furthermore, serum succinate which is elevated in cancer patients may be a theranostic biomarker for selecting patients for SUCNR-1 antagonist therapy." (PMID 36344992, 2022). "In addition to its role in cancer development through epigenetic events, succinate is an extracellular signal transducer that modulates immune response, angiogenesis and cell invasion by activating its cognate receptor SUCNR1." (PMID 33916314, 2021). "However, very little is known about the expression and role of SUCNR1 in cancer." (PMID 33113952, 2020). "Activation of SUCNR1 on TAMs, for instance, activates PI3K signaling and HIF-1α activation, triggering M2 TAM polarization and leading to immune suppression and cancer and TAM cell migration." (PMID 39796781, 2025). "Activated SUCNR1 can trigger the PI3K–HIF–1α pathway to further promote the migration, invasion, and metastasis of cancer cells." (PMID 38139250, 2023). "Additional investigations are needed to elucidate the mechanism by which SUCNR-1 is upregulated in cancer cells and to evaluate the effects of suppressing SUCNR-1 upregulation on cancer metastasis." (PMID 36344992, 2022).
cancer (continued). "However, one study found increases in serum succinate in HNSCC patients as well as increases in expression of SUCNR1 and SDH in cancer cells and surrounding stroma." (PMID 38273844, 2023). "Several studies have described that succinate-activated SUCNR1 transmits signals via non-canonical signaling pathways such as PI3K that selectively promotes cancer cell migration or metastasis." (PMID 37345199, 2023). "The succinate–SUCNR1 axis and its downstream signaling are not fully elucidated in cancer." (PMID 36551549, 2022). "In addition to the C3, for these genes (CXCL8, CX3CR1, GRM8, HTR1B, HTR1D, PTGER3, SSTR1 and SUCNR1) were related to survival in the ACC and it was also could be useful in other cancers 24-31." (PMID 34220331, 2021).
infection (10 papers, 2019 to 2025). The state of being infected such as from the introduction of a foreign agent such as serum, vaccine, antigenic substance or organism. "In parallel, proinflammatory cytokines (IL-1β, TNF-α, IL-6, IFN-α, and IFN-β) were measured, only IL-6 was significantly increased following SUCNR1 knockdown upon infection." (PMID 41492386, 2025). "Infection with the wild-type SUCNR1 effectively rescued the defective vascularization, whereas infection with the N4A mutant showed a significantly smaller vascular area." (PMID 35883628, 2022). "SUCNR1 is essential for tuft cell expansion following succinate treatment or infection with the protist Tritrichomonas." (PMID 34880874, 2021). "Of note, our lncRNA microarray analysis showed that larval E. granulosus infection can upregulate the expression of SUCNR1 and ACOD1 in adipose tissues of mice, which is paralleled with the M2 macrophage polarization post infection." (PMID 35281054, 2022). "Infection with the protist Tritrichomonas muris also induces a tuft cell response, through Trpm5 activation involving the succinate GPCR (Sucnr1/GPR91)." (PMID 40257648, 2025). "Even though helminths may be able to produce succinate during infection, helminth‐derived succinate does not induce SUCNR1 signalling." (PMID 31107965, 2019).
metabolic disease (7 papers, 2019 to 2024). A congenital disorder (due to inherited enzyme abnormality) or acquired (due to failure of a metabolically important organ) disorder resulting from an abnormal metabolic process. "Overall, these data indicate that islet SUCNR1 is associated with changes in metabolic status, implying a potential role of this receptor in the pathophysiology of metabolic disorders and T2D." (PMID 38713514, 2024). "The transient increase in succinate levels, which appears to be essential for regulating physiological responses to exercise and feeding via SUCNR1, differs notably from the consequences of chronic succinate elevation that are observed in metabolic disorders." (PMID 38182909, 2024). "Along these lines, decreasing the higher levels of circulating succinate acting on its intestinal source, rather than directly activating SUCNR1, has recently emerged as a potential strategy for treating metabolic diseases." (PMID 38713514, 2024).
neurodegenerative disease (1 paper, 2019). A disorder of the central nervous system characterized by gradual and progressive loss of neural tissue and neurologic function. "Others, like SUCNR1, have established functions in inflammatory pathways, but are not known to be associated with neurodegenerative diseases." (PMID 31214167, 2019).
SUCNR1 also shares sentences with these, for which no sentence is quoted: cardiac hypertrophy (6 papers); fibrosis (4); metabolic syndrome (3); myocardial ischemia (3); breast carcinoma (2); Cirrhosis (2); clear cell carcinoma (2); gastric cancer (2); heart failure (2); idiopathic pulmonary fibrosis (2); kidney disease (2); non -alcoholic steatohepatitis (2); non-alcoholic fatty liver disease (2); retinopathy (2); ulcerative colitis (2); vitiligo (2); alveolitis (1); aneurysm (1); cognitive deficits (1); coronary artery disease (1); endometrial cancer (1); endometrial ovarian cancer (1); endometrioid ovarian cancer (1); focal epilepsy (1); gastrointestinal stroma tumors (1); genetic disorder (1); heart diseases (1); hematologic malignancies (1); hemochromatosis (1); hypercholesterolaemia (1).
A further 26 diseases each share a sentence with SUCNR1 in 1 paper.